VEGFA (vascular endothelial growth factor A)
Diseases named in the same sentence as VEGFA in open-access papers (continued):
Sharing a sentence is not in itself a finding about the gene and the disease.
tumor (continued). "Although over-expression of ectopic VEGFA was able to partially rescue the tumor growth from the suppression by EFEMP1, restoration of tumor growth rates were far from complete." (PMID 21955618, 2011). "Heparin-binding vascular endothelial growth factor-A (VEGF-A; VEGF) is a key angiogenic factor in hypoxia, wound healing, inflammation, and tumor development." (PMID 21091776, 2010). "One of the key angiogenic factors is the vascular endothelial growth factor-A (VEGF-A), which promotes tumour neovascularisation." (PMID 16641910, 2006). "Vascular endothelial growth factor-A and its receptor KDR were expressed in the tumour cells of about half the cases, whereas Flt-1 expression was rarely observed (16%)." (PMID 15841074, 2005). "After 2 weeks, VMP1‐OE + BEV treatment profoundly suppressed tumor growth compared to the vehicle control and prolonged the overall survival of mice, suggesting that BEV could abrogate the VEGFA‐dependent oncogenic effect in VMP1‐driven tumors." (PMID 41589276, 2026). "We demonstrate that VMP1 is overexpressed in gliomas and could confer survival advantages through enhanced angiogenesis, and that bevacizumab (BEV), a VEGFA‐targeted therapy, effectively suppresses VMP1‐driven tumor growth." (PMID 41589276, 2026). "VEGFA is recognized as one of the most potent angiogenic factors, and the VEGFA/VEGFR pathway plays a crucial role in promoting the development of vascular endothelial cells during tumor angiogenesis." (PMID 41583504, 2026). "Other circulating miRNAs upregulated in ESCC include miR-25, which supports tumor progression by repressing several tumor-suppressor genes and activating the TGF-β, VEGFA/VEGFR, EGF/EGFR, and Wnt/β-catenin signaling pathways, which are fundamental for angiogenesis and metastasis." (PMID 41596525, 2026). "In our study, analysis of public datasets reveals a positive correlation between LRRC1 and VEGFA, which drives us to hypothesize the linkage between LRRC1 and tumor angiogenesis." (PMID 41369408, 2025). "Additionally, CAF-derived VEGFA upregulates METTL3 in NSCLC cells and activates the AKT/NF-κB pathway via RAC3, further promoting m6A methylation and enhancing tumor migration and invasion." (PMID 40740874, 2025). "PRAT also modulates vascular endothelial growth factor A (VEGFA), vascular endothelial growth factor D (VEGFD), Jagged 1 (JAG1), and transforming growth factor β1 (TGF-β1) activity in the tumor niche, promoting tumor angiogenesis and, consequently, cancer cell growth and metastasis." (PMID 40227577, 2025). "The hypoxic tumour microenvironment upregulates the expression of CCL28 in many tumours and thereby promotes the infiltration of CCR10 expressing Treg cells, which secrete vascular endothelial growth factor A (VEGF-A) and promote angiogenesis and metastasis." (PMID 40852716, 2025). "Coincidentally, the preliminary analysis of public datasets indicates a positive correlation between LRRC1 and VEGFA, prompting us to hypothesize and verify the linkage between LRRC1 and tumor angiogenesis." (PMID 41369408, 2025). "Likewise, PAK1KD cancer cells exhibited reduced VEGFA levels, contributing to the reduced angiogenesis and increased vascular normalisation observed in PAK1KD tumours." (PMID 41294859, 2025). "Furthermore, activation of the STAT3 pathway leads to increased secretion of vascular endothelial growth factor A (VEGFA), enhancing angiogenesis and further facilitating tumor metastasis." (PMID 40474298, 2025). "In addition to this highly inflammatory phenotype, expression of other pro-inflammatory genes, such as IL1B, CXCL16, VEGFA and HBEGF, which can facilitate tumor progression and survival, were also observed." (PMID 41056512, 2025). "VEGFA is well documented as a key cancer driver that is secreted by both cancer cells and cancer stromal cells in the TME and that not only promotes tumor angiogenesis but also suppresses tumor immune responses." (PMID 40906526, 2025).
tumor (continued). "Consequently, VEGFA expression and secretion within HCC cells were enhanced, promoting angiogenesis in the tumor tissues and accelerating disease progression." (PMID 40726441, 2025). "Bevacizumab functions as a monoclonal antibody designed to target vascular endothelial growth factor A (VEGF-A), blocking its interaction with vascular endothelial growth factor receptor (VEGFR) and inhibiting angiogenesis, a process that supports tumor growth." (PMID 40989683, 2025). "Based on these findings, we propose that USP13 may inhibit VEGFA expression by deubiquitinating and stabilizing PTEN, ultimately reducing tumor angiogenesis in CRC cells." (PMID 40746889, 2025). "This compressive environment can lead to compensatory activation of VEGFA, a cytokine important in angiogenesis, in the CAF population, which creates a chemotactic gradient encouraging angiogenesis to the increasingly necrotic core as the tumor develops." (PMID 41199904, 2025). "Finally, neutrophils in the TME secrete vascular endothelial growth factor A (VEGFA) and matrix metalloproteinase 9 (MMP9), promoting tumor growth by supporting angiogenesis and invasion." (PMID 40004489, 2025). "Moreover, TAMs facilitate the recruitment/activation of ECs via a variety of secreted factors, such as VEGFA and CXCL8, to ensure an “economic benefit” for tumor growth by supplying tumor cells with nutrition." (PMID 41346571, 2025). "FSP-1+ CAFs have been shown to promote tumor angiogenesis and cell motility and metastasis by producing ECM proteins and secreting cytokines, including tenascin C, matrix metalloproteinases, and vascular endothelial growth factor-A." (PMID 40869109, 2025). "Altered molecular targets, such as E-cadherin (CDH1), MMP9, Survivin (BIRC5), Cytokeratin 5 (KRT5), VEGFA, IL15, TNF-α (TNF), TRAIL (TNFSF10), and Tenascin-C (TNC), exhibited increased expression in our study, which correlates with their upregulation in tumor samples from individuals with OC." (PMID 40072102, 2025). "To confirm the role of VEGFA co-phagocytosis via BsAb-induced ADCP in improving antitumor responses to the BsAbs leading to a survival benefit, we examined the extent to which inhibition of ADCP affected tumor responses to the antibody treatments." (PMID 40906526, 2025). "Unlike Bevacizumab (a humanized IgG1 monoclonal antibody targeting VEGFA), our study indicates that SLC9A2 can inhibit VEGFA synthesis, effectively blocking VEGFA production at its source and serving as a superior target for anti-tumor angiogenesis strategies." (PMID 40474298, 2025). "This suggests a model in which LRRC1 activates a parallel VEGFA/VEGFR2 axis that sustains angiogenesis and tumor growth even when primary pathways—such as RAF/MEK/ERK signaling or other receptor tyrosine kinases—are inhibited by sorafenib or other drugs, ultimately leading to treatment resistance." (PMID 41369408, 2025). "Beyond single anti-angiogenic therapy, the combination of VEGFA neutralization and angiopoietin 2 (ANGPT2) inhibition has been shown to normalize tumor vasculature, which can improve drug delivery, increase sensitivity to radiation therapy, and enhance immune cell infiltration in TME." (PMID 39849659, 2025). "Mechanistically, these observations align with bioinformatic analyses highlighting PDGFRβ as an upstream regulator of multiple downstream effectors—PPARγ, VEGFA, ANG-2, VIM, COL1A1, and Cadherins all integral to tumor progression, angiogenesis, and cellular plasticity." (PMID 40282535, 2025). "In addition, the levels of CXCL1, CXCL8, VEGFA, and VEGFB related to monocyte recruitment and angiogenesis were higher in patients with advanced stages than in those with tumor stage 1." (PMID 40860188, 2025). "Mechanistically, WTAP promotes VEGFA expression via a YTHDC1-dependent RNA splicing mechanism and activates the MAPK signaling cascade, which synergistically drives tumor angiogenesis and metastatic progression, underscoring its critical role in colorectal cancer oncogenesis." (PMID 40986143, 2025).
tumor (continued). "Meanwhile, integrin αvβ5 promotes VM formation by binding to vitronectin in the ECM and activating the FAK signaling pathways, which subsequently upregulate VEGFA and MMP9 expression, enhancing tumor cell migration, invasion, and the formation of tubular VM structures." (PMID 41019994, 2025). "Subsequently, tRF‐34‐P4R8YP9LON4VHM could enhance HCC proliferation, migration, invasion, and tumour cell‐induced angiogenesis by activating the MEK/ERK signalling pathway and promoting the secretion of VEGFA." (PMID 40263693, 2025). "To investigate this, we performed ELISA analysis for the primary pro-angiogenic substrates for each of these receptors (VEGFA, PDGF-BB and FGF-2), in tumour-conditioned media, with growth factor production from HFF1 cells also assessed by way of non-tumourigenic reference." (PMID 40469193, 2025). "PFKFB3 expression is upregulated in tumor endothelial cells (TECs), and blocking the enzyme decreased melanoma metastasis and improved EC barrier integrity, independent of the presence of VEGFA." (PMID 39567756, 2025). "Furthermore, Vascular Endothelial Growth Factor A (VEGFA) plays a crucial role in the induction of cell proliferation and angiogenesis, facilitating the transport of nutrients essential for tumor growth." (PMID 40143207, 2025). "Similarly, MC0 (Cathepsin G+Tryptase+) decreased from distal normal tissues to the tumor-normal interface to the tumor core, whereas the reverse was true for MC4 (VEGFA+Tryptase+)." (PMID 39840068, 2024). "PHF5A is a tumor promoter in ESCC, which is dependent on VEGFA and PI3K/AKT signaling." (PMID 38429756, 2024). "Notably, the enrichment of VEGFA-VEGFR2 signaling pathway, a major driver of tumor angiogenesis and metastasis indicates its prominent role in GBM mechanism." (PMID 39315277, 2024). "The results presented here show the lack of VEGFA expression in tumor endothelial cells and disclose the role of VEGFA/KDR signaling in neo-vascularization of cRCC." (PMID 39000466, 2024). "Additionally, vascular endothelial growth factor A (VEGF-A) plays a crucial role in tumor angiogenesis, influencing tumor growth and serving as an unfavorable prognostic indicator for tumor-free survival." (PMID 38678209, 2024). "Herein we found inhibition of CTU2 expression decreased VEGFA protein and mRNA expression, which indicated that CTU2 may promote CAF presentation and take part in tumor vascular development." (PMID 38630355, 2024). "Moreover, the increased tumor size and lung metastatic foci induced by YTHDF2 overexpression were impaired after inhibiting PD‐L1 or VEGFA expression in Hepa1‐6 cells, and these effects were most obvious when both PD‐L1 and VEGFA were downregulated." (PMID 38247171, 2024). "Immunohistochemistry was applied to detect the expression of CD31 and VEGFA proteins in the tumor tissues, and the results showed that the expression levels of CD31 and VEGFA in the tumor tissues of the methionine-restricted diet group were significantly higher than those of the control group." (PMID 39488622, 2024). "Traditionally, bevacizumab’s impact was understood mainly in terms of its effect on the tumor’s blood supply through VEGFA inhibition, but this does not fully explain the lack of sensitivity observed in certain highly vascularized tumors among some patients." (PMID 38716237, 2024). "KLF5 may regulate VEGFA, a KLF5 target that mediated KLF5’s role in angiogenesis, expression, and tumor angiogenesis in vivo." (PMID 38602556, 2024). "Elevated levels of VEGFA and FGF can promote immune rejection of tumours." (PMID 40135140, 2024). "None of the 811 cRCCs displayed a positive VEGFA immunoreaction either in stromal endothelial or tumor cells." (PMID 39000466, 2024). "VEGFA can further induce the expression of neuropilin 1 (NRP1) in Tregs, which promotes the aggregation of Tregs around tumor blood vessels, thereby promoting Treg aggregation around tumor blood vessels." (PMID 38500876, 2024).
tumor (continued). "Therefore, we set out to investigate the contribution of VEGFA to TNBC CSC functions and its role in tumor cell-macrophage crosstalk." (PMID 38169627, 2024). "Vascular endothelial growth factor A (VEGFA) serves as a key regulator, stimulating the formation and expansion of tumor blood vessels to supply essential nutrients and oxygen, thereby promoting rapid tumor growth and metastasis." (PMID 39314630, 2024). "VEGFA expression was not correlated with the expression of other pro-angiogenic genes, the clinicopathologic tumor features, and the overall survival of patients." (PMID 39302921, 2024). "The results showed significant reductions in VEGFA, FGF2, and ANGPT concentrations in the CAR-M group, suggesting that CAR macrophages might modulate the tumor microenvironment by regulating angiogenic factors." (PMID 39592929, 2024). "Furthermore, through analysis of the GEPIA database, we observed a significant positive correlation in the expression of VEGFA and RGC‐32 in PC tumor tissues." (PMID 39606802, 2024). "Furthermore, VEGFA, KDR, CXCR1 and CXCR2 were significantly upregulated in tumour samples compared with paired normal samples, except for VEGFB, whose expression was not statistically significant." (PMID 38426619, 2024). "One of the significant challenges in clinical cancer therapy is the development of tumor radioresistance, which is influenced by factors such as increased expression of gene signaling pathways, hypoxia-inducible factor 1 (HIF-1), and vascular endothelial growth factor-A (VEGF-A)." (PMID 39030525, 2024). "In the tumor microenvironment, elevated hypoxia and metabolic stress could lead by poor diffusion of tumor ECM, leading to upregulation of TGF-β and VEGFA, which are commonly considered as immunosuppressive factors." (PMID 38385949, 2024). "Additionally, XPO1+ Epithelial can promote angiogenesis via VEGFA-VEGFR1/R2, thereby facilitating tumor growth, which aligns with our previous study." (PMID 39712016, 2024). "TGF-β, VEGFA were known to promote tumor-cell EMT and metastasis, respectively, and secreted cathepsins such as Cathepsin L and Cathepsin B were reported to facilitate tumor-cell invasion." (PMID 38926796, 2024). "Notably, studies have shown that vascular endothelial growth factor A (VEGFA) can enhance the self-renewal of cancer stem cells and promote epithelial–mesenchymal transition (EMT), potentially contributing to tumor metastasis in BC cells." (PMID 39411137, 2024). "BMAL1 drives the transcription of VEGFA conferring resistance to bevacizumab treatment, therefore combining bevacizumab with a CRY2 stabilizer (SHP1705) to inhibit BMAL1 activity led to a decreased tumor volume and an improved OS in mouse models." (PMID 39199569, 2024). "Recent reports have demonstrated that miR-138-5p exerts a repressive effect on the proliferation of endothelial progenitor cells by inhibiting hypoxia-inducible factor-1α (HIF-1α) and vascular endothelial growth factor A (VEGFA), both master regulators of angiogenesis and tumor vascular mimicry." (PMID 39596302, 2024). "Bevacizumab targets vascular endothelial growth factor A (VEGFA), a protein expressed in a variety of tumors including EAC stimulating the formation of new blood vessels, which are essential for the supply of nutrients and oxygen to the tumor." (PMID 39421768, 2024). "HIF expression may facilitate tumor metastasis, possibly because HIF1 stumulates the expression of Vascular Endothelial Growth Factor-A (VEGF-A), which related to tumor angiogenesis." (PMID 38586328, 2024). "Since GB tumors are also characterized by a high VEGF secretion profile, we explored the impact of EU and BCA, alone or in combination, on the expression of VEGFA mRNA levels, a gene upregulated in GB cells and involved in tumor growth and vascularization." (PMID 39796096, 2024).
tumor (continued). "Neutrophils of cluster 3 (Neu_C3_VEGFA, CD74+/HLA‐DRA+) displayed a mixed phenotype with angiogenesis, lipid metabolism‐related, and antigen‐presentation characteristics and they enriched in both the leading‐edge and tumor‐core region." (PMID 39716897, 2024). "In addition to promoting tumor cell proliferation, leptin signaling activation upregulates cancer cell production and secretion of soluble VEGFA via NFκB, Sp1, and HIF-1α signaling to induce angiogenic sprouting into the growing tumor mass." (PMID 39439572, 2024). "However, the majority of these drugs target the vascular endothelial growth factor A (VEGFA)/VEGF receptor 2 (VEGFR2) pathway and have shown mixed outcome, largely due to development of resistances and increased tumour aggressiveness." (PMID 38256941, 2024). "In addition, the signaling pathway involving HIF-1α, its downstream factor VEGFA, and its receptor VEGFR has received considerable attention for its role in promoting tumor growth and metastasis." (PMID 39149033, 2024). "Interestingly, ILCs, particularly ILC3s, in the inflammatory or tumor microenvironment of patients with IBD or CRC expressed significantly higher levels of CTNNB1, and Wnt/β-catenin downstream genes TCF7, VEGFA and MYC, as compared with control tissues." (PMID 38561332, 2024). "When C21 (VEGFA+ macrophages) acted as the ligand, there was communication within the tumor but not nontumor tissue with endothelial cell (C48) receptors." (PMID 39761010, 2024). "Furthermore, substantial evidence supports the involvement of VEGFA/VEGFR2 autocrine and paracrine responses in endothelial and tumor cells during tumor progression." (PMID 38474195, 2024). "The expression of VEGFA in the xenograft tumor also revealed that sh-ANXA9 and sh-S100A4 could decrease the expression of VEGFA." (PMID 38609357, 2024). "In turn, TAM recruit or activate endothelial cells to produce vascular endothelial growth factor A (VEGF-A), epidermal growth factor (EGF), C-X-C motif chemokine ligand 8 (CXCL8), and CXCL12 to promote tumor angiogenesis and continuously provide nutritional support for malignant cells." (PMID 37968342, 2024). "In addition, we also identified several key genes involved in tumor aggressiveness, including COL5A1, VEGFA, TNC, and FN1." (PMID 38390494, 2024). "In accordance with the observation in the tumor-bearing mice, VE-cadherin shapes were not altered in response to VEGFA injection in the Vegfr2Y949F/Y949F dermis." (PMID 38148112, 2024). "By elucidating the role of VEGFA and related pathways in HCC, new therapeutic approaches may be developed to inhibit tumor growth and metastasis, which may ultimately improve patient prognosis." (PMID 39319846, 2024). "Moreover, pathway analysis revealed that SPP1+APOE+ TAM were regulated by the HIF-1 signaling pathway, inducing expression of VEGFA, LDHA, and ALDOA46,47, which not only promotes hypoxia but is another approach to induce EMT in tumor cells." (PMID 39075108, 2024). "Meanwhile, inhibition of miR-664a-3p could significantly decrease the expression of HIF-1α, VEGFA, and VEGFC, which have been reported to act as factors that contribute to tumour angiogenesis." (PMID 38035445, 2024). "However, the expression of genes participating in AP (e.g., HLA‐DRA/DMB and CD74) and anti‐tumour immunity (e.g., GBP1, IFNG and TNFRSF9) were significantly higher in the TS, while genes involved in angiogenesis (e.g., VEGFA) was significantly higher in TN." (PMID 37491740, 2023). "In KIRP, VEGFA, VEGFC, and PGF were differentially expressed across tumor stages." (PMID 37852616, 2023). "Tumor cells use alternative pro-angiogenic factors independent of the VEGFA/VEGFR pathway to resist conventional anti-angiogenic therapies." (PMID 37508458, 2023). "However, VEGFA and PGF were up-regulated in tumor tissues across most cancers including BRCA and HNSC (p < 0.001)." (PMID 37852616, 2023).